XKR6 (XK related 6)
Synonyms: C8orf21; C8orf5; C8orf7; XRG6
Tractability: Antibody: UniProt places it where antibodies can reach, with medium confidence; UniProt predicts a signal peptide or a membrane-spanning region; its Gene Ontology location is reachable by antibodies, with medium confidence.
Gene: Protein-coding gene on chromosome 8 (10,896,045 to 11,201,833, reverse strand). Ensembl gene ENSG00000171044.
Subcellular location: Cell membrane
Subcellular location (Human Protein Atlas): Actin filaments
Gene Ontology:
Biological process: apoptotic process involved in development; engulfment of apoptotic cell; phosphatidylserine exposure on apoptotic cell surface
Cellular component: plasma membrane; membrane
Genetic constraint (gnomAD): Loss-of-function variants: 22 observed, 49.19 expected, observed/expected ratio (o/e) 0.45, 90% interval 0.32 to 0.64. The synonymous counts are far from expectation, so gnomAD's model fits this gene poorly and the ratio says little. Missense variants: 852 observed, 840.06 expected, observed/expected ratio (o/e) 1.01, 90% interval 0.96 to 1.07. Synonymous variants: 524 observed, 376.25 expected, observed/expected ratio (o/e) 1.39, 90% interval 1.3 to 1.5.
Homologues: Orthologues: chimpanzee XKR6 (99% identical), rabbit XKR6 (95% identical), dog XKR6 (95% identical), mouse Xkr6 (94% identical), rat Xkr6 (94% identical), pig XKR6 (93% identical), tropical clawed frog xkr6 (79% identical), zebrafish xkr6b (69% identical), zebrafish xkr6a (69% identical), guinea pig XKR6 (57% identical). Paralogues in human: XKR4 (45% identical), XKR7 (45% identical), XKR5 (19% identical), XKR8 (18% identical), XKR9 (15% identical).
Diseases named in the same sentence as XKR6 in open-access papers:
XKR6 is named in the same sentence as 34 diseases in open-access papers, as found by Europe PMC text mining. Sharing a sentence is not in itself a finding about the gene and the disease. The quoted sentences say what the papers report.
systemic lupus erythematosus (4 papers, 2018 to 2023). An autoimmune multi-organ disease typically associated with vasculopathy and autoantibody production. "For ‘childhood onset systemic lupus erythematosus’ (2 genes in GWAS) we found one overlap for XKR6." (PMID 37048133, 2023). "In a systemic lupus erythematosus (SLE) Korean cohort with 781 patients, a hybrid approach with a GWAS array and Immunochip genotyping allowed for the sensitive detection of two SLE risk loci, XKR6 and GLT1D1, which were found to be significantly higher in childhood-onset SLE." (PMID 31231652, 2019).
ischemic stroke (2 papers, 2019 to 2022). A stroke disorder caused by obstruction of blood flow to the brain, due to thrombotic (local blood clot formation) or embolic (due to a blood clot or other material traveling from another site) event. "The XKR6 rs7819412A allele carriers had higher serum TC levels in ischemic stroke and higher serum TG levels in CAD patients than the rs7819412A allele non-carriers (P < 0.05)." (PMID 31429711, 2019). "In our research, the interaction between the XKR6 rs7819412 SNP and gender, high BMI and smoking was found and the risk of CAD and ischemic stroke was also increased." (PMID 31429711, 2019). "In our research, we proved that the XKR6 rs7819412 SNP not only contributed to serum lipid levels and increased the risk of CAD and ischemic stroke, but also interacted with several environment factors." (PMID 31429711, 2019). "The present study aimed to expound the association between the XK related 6 gene (XKR6) rs7819412 single nucleotide polymorphism (SNP) and serum lipid profiles and the risk of coronary artery disease (CAD) and ischemic stroke." (PMID 31429711, 2019). "Thus, this study was designed to understand the relationship between the XKR6 rs7819412 SNP and several serum lipid parameters and the risk of CAD and ischemic stroke in the Han Chinese." (PMID 31429711, 2019). "The genetic makeup of the XKR6 rs7819412 SNP in 1783 unrelated participants (controls, 643; CAD, 588 and ischemic stroke, 552) of Han Chinese was obtained by the Snapshot technology." (PMID 31429711, 2019). "The results of the present study showed that the genotypic and allelic frequencies of the XKR6 rs7819412 SNP were obviously different between controls and patients with CAD and ischemic stroke." (PMID 31429711, 2019). "Nevertheless, the association between the XKR6 rs7819412 SNP and blood lipid levels and the risk of CAD and ischemic stroke is not clear and not reported in the Han Chinese." (PMID 31429711, 2019).
lupus nephritis (2 papers, 2012 to 2018). Glomerulonephritis in the context of systemic lupus erythematosus.
melanoma (2 papers, 2020 to 2025). A malignant, usually aggressive tumor composed of atypical, neoplastic melanocytes. "XKR6 mutations already reported in cutaneous malignant melanoma cell lines." (PMID 32241263, 2020).
schizophrenia (2 papers, 2021 to 2022). A major psychotic disorder characterized by abnormalities in the perception or expression of reality. "ZNF804A, XKR6, and IQCE genes have also been linked to other diseases, such as bipolar disorder, schizophrenia, memory loss, longevity, blood metabolite levels, asthma, and allergic rhinitis." (PMID 36233348, 2022).
absence seizures (1 paper, 2025). "In generalized epilepsy syndrome and absence seizures, XKR6 is deleted and may be affected by CNV." (PMID 41479783, 2025).
Anxiety (1 paper, 2023). Intense feelings of nervousness, tension, or panic often arise in response to interpersonal stresses. "XKR6 was also implicated in a recent GWAS of externalizing, and a GWAS of anxiety and depression." (PMID 37173343, 2023).
atherosclerosis (1 paper, 2025). A disease characterized by the build-up of fatty material and calcium deposition in the arterial wall resulting in partial or complete occlusion of the arterial lumen. "Other notable genes included XKR6 (XK-related protein 6), implicated in apoptotic processes central to atherosclerosis, and ERI1 (exoribonuclease 1), which may influence vascular remodeling through RNA metabolism." (PMID 41299637, 2025).
breast tumors (1 paper, 2018). "Using data available from The Cancer Genome Atlas (TCGA), we correlated expression of four genes (MKRN3, TPPA, ZNF280B, and XKR6) with DNA methylation in 553 breast tumors." (PMID 30352973, 2018).
colon cancer (1 paper, 2024). "XKR6 (XK-related 6), which came second on the list, is associated with metastasis in colon cancer." (PMID 38790260, 2024).
colorectal cancer (1 paper, 2023). A primary or metastatic malignant neoplasm that affects the colon or rectum. "Among these, many have important roles in regulating the neural progenitors migration, such as deleted in colorectal cancer (DCC), XKR6 and transcription factor 4 (TCF4)." (PMID 36729042, 2023).
endometriosis (1 paper, 2025). The growth of functional endometrial tissue in anatomic sites outside the uterine body. "Through this analysis, we identified 42 genome-wide significant (5 × 10−8) genetic variants significantly associated with endometriosis, 6 of which were not reported previously: ABHD1/2p23.3, TMEM131/2q11.2, XRCC4/5q14.2, PPP1R9A/7q21.3, XKR6/8p23.1, and TRPS1/8p23.3." (PMID 40262193, 2025).
gastric cancer (1 paper, 2020). A primary or metastatic malignant neoplasm involving the stomach. "The methylation of XKR6, CCDC57, MAML3, SDC2, and CLIP4 is associated with age and tumor location in gastric cancer." (PMID 33575272, 2020).
hyperlipidemia (1 paper, 2019). "Therefore, the XKR6 rs7819412 SNP may be a new target for early prevention and treatment of hyperlipidemia and atherosclerosis-related diseases." (PMID 31429711, 2019).
opioid use disorder (1 paper, 2023). A substance-related disorder that involves the recurring use of opioids despite negative consequences. "We also detected associations near XKR6 and AFF3, which have been recently implicated in externalizing psychopathology, and PTPRF and KDM4A, recently implicated in problematic opioid use and opioid use disorder." (PMID 37173343, 2023).
tumor (3 papers, 2017 to 2025). "Immunohistochemical staining of sections from patients with PMMC revealed statistically significant increases in expression of SIRPB1, AHNAK2, and XKR6 in tumor-associated regions compared with adjacent tissue." (PMID 41479783, 2025). "AHNAK2 and XKR6 are involved in cell adhesion and signal transduction, potentially regulating interactions between tumor cells and immune cells." (PMID 41479783, 2025). "The methylation of other genes, CLIP4, XKR6, CCDC57, MAML3 and SDC2, was related with one or more of the following variables: age, tumor location, and Helicobacter pylori infection, rather than with the histologic subtype." (PMID 28418867, 2017).
neurodevelopmental disorder (1 paper, 2022). A behavioral and cognitive disorder with onset during the developmental period that involves impaired or aberrant development of intellectual, motor, or social functions. "Among the unique DMGs, we found several genes linked to neurodevelopmental disorder and ASD, including XK related 6 (XKR6), zinc finger protein 107 (ZNF107), and myeloma-overexpressed gene 2 protein (MYEOV2) in the ASD with 16.p11.2 del." (PMID 35978033, 2022).
renal disorder (1 paper, 2012). "The clearest associations were found between renal disorder and SNPs in the XKR6 and FAM167A-BLK loci." (PMID 23049788, 2012).
XKR6 also shares sentences with these, for which no sentence is quoted: allergic rhinitis (1 paper); asthma (1); bipolar disorder (1); celiac disease (1); coronary artery disease (1); depression (1); Gingival bleeding (1); hematologic disorder (1); Insulin resistance (1); Neurologic disorder (1); Obesity (1); Oral ulcer (1); periodontitis (1); Tinnitus (1); type 1 diabetes mellitus (1); type 2 diabetes mellitus (1).